SNORD115-13 (small nucleolar RNA, C/D box 115-13)
Synonyms: HBII-52-13
Gene: Small nucleolar RNA gene on chromosome 15 (25,193,321 to 25,193,402, forward strand). Ensembl gene ENSG00000273835.
Gene Ontology:
Biological process: RNA processing
Cellular component: nucleolus
Homologues: Orthologues: macaque SNORD115 (99% identical). Paralogues in human: SNORD115-12 (99% identical), SNORD115-16 (99% identical), SNORD115-40 (99% identical), SNORD115-9 (99% identical), SNORD115-1 (98% identical), SNORD115-10 (98% identical), SNORD115-11 (98% identical), SNORD115-20 (98% identical), SNORD115-21 (98% identical), SNORD115-29 (98% identical), SNORD115-36 (98% identical), SNORD115-42 (98% identical), and 37 more.